LGALS3 (galectin 3)
Diseases named in the same sentence as LGALS3 in open-access papers (continued):
Sharing a sentence is not in itself a finding about the gene and the disease.
endometrial cancer (9 papers, 2014 to 2025). Primary or metastatic malignant neoplasm involving the endometrium (mucous membrane that lines the endometrial cavity). "Particularly, contradictory results have been reported from different studies on galectin-3 concentrations and expression in endometrial cancers." (PMID 36578551, 2022). "Furthermore, multiple studies have indicated that galectin-1, a homodimeric protein involved in angiogenesis and cross-linking receptors, and galectin-3, a chimaera-type protein associated with cancer metastasis and inflammatory regulation, are mainly involved in endometrial cancer." (PMID 36578551, 2022). "Galectin-3 immunoreactivity progressively decreased from normal samples (80%) to endometrial carcinoma (55%), indicating poor prognoses." (PMID 36578551, 2022). "Other studies have also noted an increased serum level of galectin-3 in patients with endometrial cancer." (PMID 33799622, 2021). "Galectin 3 can be an independent prognostic factor in patients with endometrial cancer, which would allow individualization of treatment in patients with this type of cancer." (PMID 32859099, 2020). "In order to verify the usefulness of galectin 3 as an early marker for endometrial cancer, the ROC curve was used, and the AUC was calculated for this curve." (PMID 32859099, 2020). "Detailed analysis of median serum galectin 3 concentrations depending on endometrial cancer stage revealed significant differences between FIGO III and IV vs. FIGO I and II patients." (PMID 32859099, 2020). "In human endometrial cancers, the expression of galectin-1 is upregulated in uterine adenocarcinomas compared with normal adjacent endometrium, whereas expression of galectin-3 is downregulated in endometrial cancer cells compared with normal mucosa." (PMID 29389859, 2018). "In contrast, galectin-3 expression was significantly decreased in endometrial cancer." (PMID 36578551, 2022). "Galectin-3 expression seems to be reduced in endometrial cancer compared to normal endometrium." (PMID 33799622, 2021). "Moreover, vaspin was found to have the greatest specificity and sensitivity for endometrial cancer (83% and 89%, respectively) when compared to other adipokines, including leptin, galectin-3 and omentin-1." (PMID 33799622, 2021). "Moreover, it has been noted that serum galectin-3 levels were strictly related to endometrial cancer stage and varied significantly between patients with FIGO III and IV vs. FIGO I and II." (PMID 33799622, 2021). "Multivariate analysis carried out as a part of our study revealed that galectin 3 may be an independent prognostic factor for endometrial cancer." (PMID 32859099, 2020). "Galectin 3 can be an independent prognostic factor in patients with endometrial cancer." (PMID 32859099, 2020). "In addition, the median serum concentration of galectin 3 was significantly higher in the group of patients with endometrial cancer as compared to patients with normal endometrium (p = 0.002)." (PMID 32859099, 2020). "Our research failed to confirm that galectin 3 can be used as a good diagnostic test for use in endometrial cancer screening." (PMID 32859099, 2020). "In many endometrial cancers, galectin-3 expression is reduced, and low levels of galectin-3 may be involved in the transformation of normal endometrium into carcinoma." (PMID 32033052, 2020). "No similar studies assessing the serum galectin 3 levels in endometrial cancer are available in the literature." (PMID 32859099, 2020). "To our knowledge, this is the first paper to describe the presence of PD-L1 and PD-L2 in endometrial cancer as such, and we are not aware that any of the currently described molecules have been described in uterine sarcoma so far, except for possibly IDO, galectin-1 and galectin-3." (PMID 24658839, 2014).
infarction (9 papers, 2017 to 2025). A localised pathological necrosis of tissue resulting from obstruction of the blood supply usually by a thrombus, an embolus, or vascular torsion. "Galectin-3 (Gal-3) is a novel biomarker of cardiac fibrosis after infarction that is released by the inflammation process." (PMID 39619937, 2024). "The use of galectin-3 as a potential therapeutic target in the treatment of heart fibrosis after infarction may bring many benefits." (PMID 35053194, 2021). "They demonstrated that serum galectin-3 concentration was significantly higher in AIS patients compared with healthy individuals, what increased the intensity of AIS and infarction volume." (PMID 35053194, 2021).
retinal degeneration (9 papers, 2015 to 2025). Degeneration of the retina. "We wondered if galectin-3 was relevant specifically for inherited retinal degeneration due to MERTK deficiency." (PMID 35711472, 2022). "Using the light-induced retinal degeneration model, an established mouse model to study key aspects of dry AMD, we show that genetic deficiency and pharmacological inhibition of galectin-3 both can diminish microglia reactivity and delay light-induced retinal degeneration." (PMID 36115971, 2022). "Thus, loss of galectin-3 significantly delays retinal degeneration in this light-damage paradigm." (PMID 36115971, 2022). "For example, recent research has shown that TREM2-mediated upregulation of galectin-3, also contributes to the phagocytic activity of microglial cells during retinal degeneration." (PMID 39187498, 2024). "Microglia activation is a hallmark of retinal degenerative diseases and we have previously demonstrated that pharmacological or genetic modulation of microglia-related genes including TSPO and galectin-3 can delay retinal degeneration." (PMID 38288111, 2023). "This study defines galectin-3 as a potent driver of retinal degeneration and highlights the protein as a drug target for ocular immunomodulatory therapies." (PMID 36115971, 2022). "We found excess protein levels of galectin-3 in Müller cells in the mertk−/− model of retinal degeneration at an age prior to detectable photoreceptor distress or any retinal abnormality, let alone overt retinal degeneration." (PMID 35711472, 2022). "Our findings demonstrate that increased galectin-3 in microglia contributes to inflammation and disease progression, while targeting galectin-3 by genetic or pharmacological approaches ameliorates light-induced retinal degeneration." (PMID 36115971, 2022). "In this report, we define a novel role for galectin-3 in retinal degeneration and blinding diseases." (PMID 36115971, 2022). "Altogether, our results from both inherited and acutely induced models of retinal degeneration agree that eliminating galectin-3 exacerbates Müller cell activation and retinal degeneration." (PMID 35711472, 2022). "To determine if galectin-3 modulates microglia activity during light-induced retinal degeneration, we used galectin-3 (Lgals-3) KO mice." (PMID 36115971, 2022). "To elucidate the role of galectin-3 in retinal inflammatory diseases, we studied the light-induced retinal degeneration model mimicking key features of dry AMD including microgliosis and photoreceptor cell death." (PMID 36115971, 2022). "Altogether, our results from two distinct models of retinal degeneration support a supportive role for galectin-3 in Müller glia modulation that serves to protect the retina in disease." (PMID 35711472, 2022). "In this study, we have explored the contribution of Galectin-3 to the retinal degeneration observed in a chronic carotid stenosis model, which in the brain has been used as a model of vascular dementia." (PMID 25968897, 2015). "To validate the findings from genetic knockout with a translational therapy approach, we studied whether pharmacological inhibition of galectin-3 effectively attenuates microgliosis and retinal degeneration." (PMID 36115971, 2022). "Here, we hypothesized that genetic deficiency of galectin-3 or its modulation via TD139 dampens mononuclear phagocyte reactivity and delays retinal degeneration." (PMID 36115971, 2022). "Altogether, these results indicate that lack of galectin-3 causes excessive activation of Müller glia prior to microglia activation and leads to more severe retinal degeneration due to MERTK deficiency." (PMID 35711472, 2022). "Altogether, lack of galectin-3 causes overactivation primarily of Müller glia and worsens retinal injury, and this is not specific to retinal degeneration due to loss of the galectin-3 receptor MERTK." (PMID 35711472, 2022). "Therefore, we wanted to explore the contribution of Galectin-3 (Gal-3) to hypoperfusion-induced retinal degeneration in mice." (PMID 25968897, 2015).
retinal degeneration (continued). "We found that galectin-3 expression was strongly upregulated in reactive retinal mononuclear phagocytes of AMD patients and in the two related mouse models of light-induced retinal degeneration." (PMID 36115971, 2022). "Targeting of galectin-3 by genetic knockout or using the small-molecule inhibitor TD139 could limit microglia reactivity and reduce retinal damage in these two different mouse models of light-induced retinal degeneration." (PMID 36115971, 2022). "Moreover, DKO mice lacking both galectin-3 and MERTK show significantly more pronounced Müller glia activation and retinal degeneration compared to mice lacking MERTK alone." (PMID 35711472, 2022).
Venous thrombosis (9 papers, 2017 to 2025). Formation of a blood clot (thrombus) inside a vein, causing the obstruction of blood flow. "Consistently, galectin-3 and Gal3-BP-deficient mice showed significantly reduced deep venous thrombosis." (PMID 36873388, 2023). "Using mouse stasis models of venous thrombosis, galectin-3 and its binding protein (Gal3-BP) were detected on vein walls, red blood cells, platelets, and microparticles, contributing galectin-3 functions to venous thrombosis." (PMID 36873388, 2023). "A direct correlation between blood plasma levels of galectin-3/Gal3-BP and pro-inflammatory cytokines and chemokines was observed in patients with deep venous thrombosis." (PMID 36873388, 2023). "Similar to previous data on venous thrombosis, an abundant amount of galectin-3 was stained in the thrombus samples from occluded AV shunts." (PMID 31080833, 2019). "Its role in the vasculature is not well understood, but it has recently been shown to play a proinflammatory role in human venous thrombosis via its binding to galectin 3, enhancing leukocyte adhesion to the vessel wall and increasing IL-6 expression." (PMID 28319050, 2017). "Additionally, studies have shown that galectin-3 exhibits prothrombotic and proinflammatory properties in the context of experimental venous thrombosis." (PMID 40149705, 2025). "In venous thrombosis, galectin-3 BP and galectin-3 play critical roles, possibly through IL-6 and PMN-mediated thrombotic mechanisms, and are potential biomarkers in human venous thrombosis." (PMID 31080833, 2019).
acute lymphoblastic leukemia (8 papers, 2015 to 2025). Leukemia with an acute onset, characterized by the presence of lymphoblasts in the bone marrow and the peripheral blood. "In acute lymphoblastic leukemia (ALL), EV-mediated transfer of galectin 3 (GAL3) from stromal cells to ALL cells stimulates endogenous GAL3 expression, which confers protection against drug treatment." (PMID 37371477, 2023). "We recently showed that Galectin-3 levels in bone marrow plasma of B-cell precursor acute lymphoblastic leukemia (BP-ALL) samples are elevated compared to controls." (PMID 29580262, 2018).
atopic dermatitis (8 papers, 2017 to 2025). "Galectin-3 is a pro-inflammatory mediator in atopic dermatitis, needed for the inflammatory response to epicutaneous antigens via its impact on T cells." (PMID 33150039, 2020).
Autoimmunity (8 papers, 2015 to 2023). The occurrence of an immune reaction against the organism's own cells or tissues. "There is mounting evidence that galectin-3 is a prognostic and diagnostic biomarker associated with diverse diseases and conditions, including cancer, cardiovascular disease, autoimmunity, wound healing, allergic disease, and chronic inflammation in general." (PMID 33154744, 2020). "Galectin-3 has numerous pivotal roles in autoimmunity, kidney disorders immunometabolism, tumor progression." (PMID 32455781, 2020). "Galectin-3 (Gal-3) is a carbohydrate binding lectin, with multiple roles in inflammatory diseases and autoimmunity including its antiapoptotic effect on epithelial cells." (PMID 26996208, 2016).
chronic pancreatitis (8 papers, 2010 to 2025). A chronic inflammatory process causing damage and fibrosis of the pancreatic parenchyma. "However comparison between expression of galectin-3 in ductal cells in chronic pancreatitis and cancerous pancreatic tissue demonstrates that its expression was increased over normal tissue and was more uniform." (PMID 23658855, 2010).
cognitive decline (8 papers, 2019 to 2025). "A recent study has shown that microglia-derived galectin-3 influences synaptic plasticity and brain rhythmicity, which are implicated in neuroinflammation and cognitive decline." (PMID 38991663, 2024). "Galectin-3 was identified as an independent risk factor for MCI, with significant correlations to cognitive decline in T2DM patients." (PMID 39144658, 2024). "By inhibiting galectin-3, MCP reduces the brain’s inflammatory response and may alleviate cognitive decline." (PMID 39727960, 2024).
cryptococcosis (8 papers, 2017 to 2023). An acute or chronic, localized or disseminated infection by Cryptococcus neoformans. "Galectin-3 also exhibits a direct lytic effect on Cryptococcus neoformans, a fungus that causes cryptococcosis, and inhibits its growth." (PMID 37511297, 2023). "Recently, we reported that galectin-3 (Gal-3), a β-galactoside-binding animal lectin, plays significant roles in cryptococcal infection." (PMID 31019001, 2019). "Moreover, the mammalian β-galactoside-binding protein Galectin-3 (Gal-3), which is increased during cryptococcal infection, was described to inhibit C." (PMID 37223252, 2021). "Galectin-3 levels in serum are elevated in C. neoformans-infected mice, as well as in patients with cryptococcosis, both immunocompetent and HIV+, suggesting that C. neoformans drives Galectin-3 production by the host." (PMID 29518906, 2018).
diffuse large B-cell lymphoma (8 papers, 2010 to 2025). "This in marked contrast to a more mature B-lineage cancer, diffuse large B-cell lymphoma, which was reported to contain high levels of endogenous Galectin-3 mRNA." (PMID 25869099, 2015). "In this context, Hoyer and colleagues described that human tonsilar follicular dendritic cells are galectin-3+ and these cells regulate anti-apoptotic mechanisms during diffuse large B-cell lymphoma progression." (PMID 21573150, 2011). "Recently, the role of galectin-3 in the prognosis and extranodal involvement of diffuse large B-cell lymphomas (DLBCL) was demonstrated." (PMID 23658855, 2010).
experimental autoimmune encephalomyelitis (8 papers, 2016 to 2026). An autoimmune demyelinating disease of the central nervous system that is produced experimentally in animals by the injection of homogenized brain or spinal cord in Freund's adjuvant. "We previously showed that galectin-3 (gal-3) is associated with the pathogenesis of experimental autoimmune encephalomyelitis (EAE), an animal model of MS." (PMID 38607051, 2024). "In primary cultures of microglia, suppression of galectin-3 expression enhances the elimination of damaged lysosomes, and when galectin = 3 expression is eliminated in mice with experimental autoimmune encephalomyelitis (EAE), the severity of the disease is reduced." (PMID 36008956, 2022).
gestational diabetes mellitus (8 papers, 2020 to 2025). "Galectin-3 played many physiologic and pathologic roles in pregnancy-associated diseases including gestational diabetes mellitus, fetal growth restriction, infertility, and missed abortion." (PMID 37626284, 2023). "Galectin-3 is also intensely expressed at molecular levels (mRNA and protein expression) in gestational diabetes mellitus maternal blood and placental tissue, suggesting a potential galectin-3 damaging effect." (PMID 38673633, 2024). "Significantly higher galectin-3 levels were found in patients with gestational diabetes mellitus (GDM group; n = 77) during the first and second trimesters than that in healthy pregnant women (HP group; n = 113) (P < 0.05)." (PMID 37626284, 2023). "This study aims to investigate the effects of the Galectin‐3 (Gal‐3) inhibitor TD139 on inflammation and the extracellular signal‐regulated kinase (ERK)/c‐Jun N‐terminal kinase (JNK)/p38 pathway in gestational diabetes mellitus (GDM)." (PMID 39230472, 2024).
nephritis (8 papers, 2014 to 2022). Inflammation of renal tissue. "In bacterial infection, the majority of researches on bacterial infection showed that streptococcus in galectin-3 knockout mice had a higher bacterial burden and enhanced nephritis and renal dysfunction in comparison with wild-type mice." (PMID 35437453, 2022). "Serum galectin-3 levels were higher in patients with SLE, especially in those with nephritis, and correlated with anti-dsDNA titers." (PMID 27089335, 2016).
periodontal disease (8 papers, 2020 to 2025). "Both Galectin-1 and Galectin-3 seem to have outstanding diagnostic accuracy for the identification of periodontal disease, an acceptable ability to measure periodontal disease activity and the severity of inflammatory status." (PMID 38743248, 2024). "Galectin-3 and melatonin were molecules that seem to be directly linked to periodontal disease severity and COVID-19 infection." (PMID 35224542, 2022). "Galectin-3, a carbohydrate-binding protein, is known to affect the key processes involved in the pathogenesis of periodontal diseases, inflammatory/immune responses, and antimicrobial activity." (PMID 39453923, 2024). "Few clinical studies demonstrated increased expression of Galectin-3 in different forms of periodontal diseases." (PMID 33815121, 2021). "Therefore, the objective of this mini review is to discuss the possible effects of Galectin-3 on the process of immune homeostasis and the balance between oral microbial community and host response and to provide insights into the potential therapeutic targeting of Gal-3 in periodontal disease." (PMID 33815121, 2021). "A more recent finding indicates that galectin-3 and PAD4 may be involved in the pathogenesis of periodontal disease due to their elevated levels in periodontal disease." (PMID 37298447, 2023).
subarachnoid hemorrhage (8 papers, 2020 to 2024). A serious neurological disorder characterized by intracranial hemorrhage into the subarachnoid space. "Another galectin-3 inhibitor (a modified citrus pectin) has also been shown to prevent the breakdown of the blood–brain barrier and brain injury in a mouse model of subarachnoid hemorrhage." (PMID 37491623, 2023). "For example, Galectin-3 (Lgals3) is important in brain inflammatory response in neurodegenerative diseases and inhibiting galectin-3 has been proved to ameliorate brain edema in subarachnoid hemorrhage." (PMID 33504361, 2021). "A previous study showed that modified citrus pectin (a galectin-3 inhibitor) prevented mouse post-subarachnoid hemorrhage blood-brain barrier disruption, possibly inhibiting galectin-3." (PMID 33686023, 2021). "One of the few neuropathological studies addressing the role of Galectin-3 inhibitors in the brain structure showed that modified citrus pectin (Galectin-3 inhibitor) prevents breakdown of blood–brain barrier and brain injury in mouse model of subarachnoid hemorrhage." (PMID 32455781, 2020). "Recent reports indicate that in subarachnoid hemorrhage (SAH), elevated acute plasma galectin-3 levels are linked to post-SAH delayed cerebral ischemia, with no such link with vasospasm, suggesting that galectin-3 could be a prospective novel treatment or research target for brain injury after SAH." (PMID 34900086, 2021).